LRRK2 (leucine rich repeat kinase 2)
Diseases named in the same sentence as LRRK2 in open-access papers (continued):
Sharing a sentence is not in itself a finding about the gene and the disease.
tumor (continued). "The regulation of ccRCC tumor cell lines proliferation by LRRK2 was examined by CCK8 assay." (PMID 34217264, 2021). "Likewise, Western blotting results showed that the expression level of LRRK2 in ccRCC tissues was significantly higher than that in adjacent non-tumor tissues." (PMID 34217264, 2021). "Meanwhile, Kaplan–Meier analysis showed that high expression of LRRK2 correlates to a better prognosis; knockdown of LRRK2 expression attenuated the proliferation ability of ccRCC tumor cell lines; protein–protein interaction network analysis showed that LRRK2 interacts with HIF1A and EGFR." (PMID 34217264, 2021). "The shRNA diminished LRRK2 protein levels in ccRCC tumor cell lines." (PMID 34217264, 2021). "Moreover, they also confirmed that the down-regulation of LRRK2 in cultured tumor cells compromises MET activation and selectively reduces downstream MET signaling to mTOR and STAT3." (PMID 32196072, 2020). "Interestingly, these KI mice also manifested increased GI tumor development in the DSS/azoxymethane tumor model suggesting that increased LRRK2 levels and kinase activity may unleash both increased gut inflammation and tumorigenesis." (PMID 41246319, 2025). "However, the expression of pro-tumorigenic genes including Ang4, VEGF, Wnt5a and MMP-10 was comparable in the LRRK2 KI and WT control groups, suggesting that LRRK2 G2019S may promote tumor development primarily by promoting inflammation." (PMID 38607004, 2024). "Thus, the LRRK2 substance has the potential to be applied as an anti-tumor drug." (PMID 35717205, 2022). "With the cBioPortal, we conducted a more in-depth genomic analysis of 537 ccRCC patients for mutation sites of LRRK2 in tumor tissues and found that LRRK2 tends to be slightly amplified, and confirmed that there is a negative correlation between LRRK2 expression and DNA methylation." (PMID 34217264, 2021). "This is the first study to demonstrate a tumor suppressive role for LRRK2 in carcinogen-induced distal lung cancer, and to potentially identify a Parkinson’s patient population (i.e. current smokers) for whom long-term LRRK2 inhibition may require additional monitoring." (PMID 33483550, 2021). "In 88 paired samples, LRRK2, PECAM1, EPAS1, and LDB2 showed significant low expression in tumor samples, which was consistent with previous results." (PMID 32196072, 2020). "No significant clustering of LRRK2 CNV-altered versus LRRK2 CNV-unaltered cases was observed in terms of neoplasm staging." (PMID 32722212, 2020). "One hundred and fourteen matched human NSCLC tumor/normal pairs were examined by real-time q-PCR analysis for expression of PARK1/4 (SCNA), PARK2 (Parkin), PARK5 (UCHL1), PARK6 (PINK1), PARK7 (DJ-1), PARK8 (LRRK2), PARK9 (ATP13A2), PARK15 (FBXO7), and GBA mRNA." (PMID 26245297, 2015).
neurological disorders (20 papers, 2006 to 2025). "In carrying out these functions, a mutation in exon 41, which encodes the kinase domain of LRRK2, is thought to enhance the kinase activity of LRRK2, leading to neurological disorders such as PD." (PMID 36551242, 2022). "Overall, these data shed light on potential mechanisms underlying LRRK2-GS’s actions in ER stress that renders severe neurological diseases such as PD." (PMID 31046837, 2019). "Given these established links, it is worth considering that impairments in LRRK2 G2019S may create the conditions whereby immune dysregulation underlies a subtype of neurological disease with features of both MS and PD." (PMID 39175765, 2024). "LRRK2, a common genetic cause of familial and sporadic PD, shares pathogenetic and neurologic similarities with HIV-associated neurologic disorders." (PMID 31275235, 2019). "Pathologic LRRK2 activation was found to be an important mediator of neuroinflammation and neuronal damage in in-vitro and in-vivo models of HIV-associated neurologic disorders." (PMID 31275235, 2019). "Further, driving linkage-specific ubiquitination in cells also promotes LRRK2 accumulation in cytoplasmic inclusions, similar to what is seen with dephosphorylation of the upstream kinase sites and with other neurological disease proteins." (PMID 25939886, 2015). "Interestingly, LRRK2 also has a role outside neurological disorders." (PMID 39962078, 2025). "Based on previous results and the importance of non-cell autonomous pathogenic mechanisms in several neurological disorders, we generated an LRRK2 Drosophila model in which the LRRK2 expression is driven by a glial promoter (Repo-GAL4) compared to a ubiquitous promoter (Actin-GAL4) or control flies." (PMID 39062128, 2024). "Skin punch biopsies were performed on PD patients diagnosed with the LRRK2 G2019S mutation and on control subjects with no known PD-related mutations or any other neurological disorder; additional mutant fibroblasts were purchased from Coriell (ND29370; Coriell Institute)." (PMID 27640816, 2016). "To address this gap in knowledge, we examined quantitative protein pathology, glucocerebrosidase activity and lipid substrates in parallel from 4 regions of 91 brains with no neurological disease, idiopathic, GBA1-linked, or LRRK2-linked PD and DLB." (PMID 37169750, 2023). "We have attempted to use these anti-LRRK2 antibodies to detect brain LRRK2 in subjects without neurological diseases and those with sporadic PD." (PMID 17137507, 2006).
movement disorder (19 papers, 2008 to 2025). Neurological conditions resulting in abnormal voluntary or involuntary movement, which may impact the speed, fluency, quality and ease of movement. "A multicentre young onset and familial PD cohort (n = 220) from 9 movement disorder centres across Central Europe within the CEGEMOD consortium was screened for rare LRRK2 variants using whole exome sequencing data." (PMID 38854119, 2024). "A good candidate for gene therapy is movement disorders with dominantly-inherited genetic causes such as the htt gene for HD and LRRK2 or SNCA genes for PD." (PMID 33304456, 2020). "Our prevalence data for LRRK2-associated PD imply that most clinicians who treat movement disorders will treat patients with this disorder at a clinically relevant frequency." (PMID 18539534, 2008). "While the wide spectrum of mitochondrial alterations strongly implicate mitochondria in the pathology of the movement disorder, few functional studies focussed on the contribution of the organelles to the penetrance of LRRK2-PD." (PMID 38835904, 2022). "Eleven percent of LRRK2 non-manifesting carriers had dopamine transporter (DaT) deficits, with carriers showing higher Movement Disorders Society Unified Parkinson’s Disease Rating Scale scores and hyposmia rates than controls, suggesting LRRK2 as a predictive biomarker for PD development." (PMID 41050048, 2025). "None of the healthy asymptomatic LRRK2 mutation carriers (LRRK2-H) had any complaints of a movement disorder." (PMID 25309429, 2014). "In light of the likely decrease in LRRK2 MT binding in R1441G and G2019S carriers, this is an intriguing possibility, suggesting that LRRK2 might be connected to the pathogenesis of an additional movement disorder." (PMID 24275654, 2014). "We recently reported several LRRK2-based outcome measures in a cohort of G2019S-LRRK2 carriers (both healthy and affected) from the CUMC-Movement Disorders center." (PMID 35676398, 2022). "Importantly, however, human genetic studies identifying LRRK2 variants with predicted loss of function effects and reduced LRRK2 levels in heterozygous individual in the absence of any evidence of a clinical movement disorder suggests that a safe therapeutic window may exist for LRRK2 inhibition." (PMID 34030727, 2021).
bacterial infection (12 papers, 2011 to 2025). "Mutations in LRRK2 have also been shown to make individuals more susceptible to bacterial infections, suggesting that the protein that LRRK2 codes for may help our immune system." (PMID 32057291, 2020). "Furthermore, LRRK2 has been associated with bacterial infections such as Mycobacterium tuberculosis and Salmonella typhimurium." (PMID 32508566, 2020). "A role of LRRK2 in regulating inflammation and pathogen defense has been suggested by reports implicating LRRK2 in several bacterial infections." (PMID 32508566, 2020). "The dramatic decrease in lipocalin-2 levels, identified in both the plasma and urine of LRRK2 knockout rats, is a peculiar finding as lipocalin-2 has been identified to be a critical component in innate immunity to bacterial infection." (PMID 23799078, 2013). "LRRK2 is recruited near pathogens during bacterial infection, is up-regulated upon exposure to microbial and viral particles and LRRK2 deficiency impairs reactive oxygen species production during phagocytosis." (PMID 22594666, 2012). "Akin to Lrrk2, albeit less-studied in this context, α-synuclein has been reported to have anti-microbial properties both in vivo and in vitro, including to protect mice from viral and bacterial infections that have begun outside the central nervous system." (PMID 40471880, 2025). "To explore whether LRRK2 affects innate immune function, we used a model of subclinical bacterial infection." (PMID 32111741, 2020). "However, it has been reported that LRRK2 localizes to phagosomes upon bacterial infection, and that lack of LRRK2 expression reduces ROS production and enhances bacterial survival in RAW 264.7 cells." (PMID 28202666, 2017).
immune diseases (12 papers, 2015 to 2025). "As is the case for many immune diseases, associated autophagy-related genes have been identified by GWAS, such as NUPR1, IRGM, CCL2, LRRK2, MTMR3, IL23R, and NOD2." (PMID 28099919, 2017). "Multiple layers of evidence have suggested that dysfunction of LRRK2 in the immune system may be a central component for the development of immune diseases." (PMID 28099919, 2017). "Crohn's T2397M‐mutant LRRK2 patients have reportedly lower levels of LRRK2 protein activity within their immune cells 162, suggesting that one harmful side effect of a complete inhibition of LRRK2 as a treatment for PD could be the development of intestinal‐immune diseases." (PMID 25899482, 2015). "Furthermore, LRRK2 (OWAS-joint p-value = 9.0×10−16) was found to suppress the transcriptional activity of NFAT1, which has been considered a key target for treating immune disorders." (PMID 35886003, 2022).
infectious disease (12 papers, 2018 to 2025). A disorder directly resulting from the presence and activity of a microbial, viral, or parasitic agent in humans. "This suggests pleiotropic effects of the NOD2 and LRRK2 variants across neurodegenerative, inflammatory and infectious diseases." (PMID 36972292, 2023). "With LRRK2 variants also being associated with autoimmune and infectious diseases, it is unsurprising that LRRK2 is expressed in numerous immune cells such as microglia." (PMID 33309801, 2021). "In a zebrafish model, the LRRK2 mutant showed a weakened immune response to Mycobacterium marinum infection, functionally confirming the role of LRRK2 in infectious diseases." (PMID 32373110, 2020). "This study provides a cellular function underlying human genetic studies linking LRRK2 to mycobacterial infections and reveals an unexpected function for LRRK2 in macrophages and infectious diseases control." (PMID 29789389, 2018). "Overall, the finding that LRRK2 is activated by membrane damage and thereby contributes to organelle maintenance has implications for immunity and inflammation in the context of both infectious and non‐infectious diseases." (PMID 32643832, 2020). "At the moment, four genes are known, clearly implicated in autosomal dominant Parkinson’s disease—the SNCA/PARK1–PARK4 gene, the LRRK2/PARK8 gene, the VPS35/PARK17 gene, and the EIF4G1/PARK18 gene; instead, PARK-1 and DJ-1 genes are involved in the autosomal recessive transmission disease." (PMID 31817546, 2019).
inflammation (5 papers, 2015 to 2024). Aberrant reaction of the microcirculation characterized by movement of fluid and leukocytes from the blood into extravascular tissues. "We further explored the role of LRRK2 in the occurrence and development of acute liver inflammation." (PMID 38725082, 2024).
genetic diseases (4 papers, 2006 to 2025). "Therefore, gene therapy strategies for LRRK2 G2019S mutation can be used as a valuable reference to treat other genetic diseases." (PMID 36551242, 2022). "LRRK2 polymorphisms are also associated with increased risk of sporadic PD, suggesting that LRRK2 may provide understanding of the molecular mechanisms of both sporadic and genetic diseases." (PMID 31039583, 2019). "Therefore, various genetic tools for treating LRRK2 G2019S mutations, such as ZFN, HDAdV, BAC-based HR, CRISPR/Cas9, and ABE, could suggest therapeutic strategies for other genetic diseases as well." (PMID 36551242, 2022).
brain disease (3 papers, 2019 to 2025). "In conclusion, our study sheds light on the impact of LRRK2-mediated neuroinflammation on neurons in a context related to PD and AD and, importantly, suggests that targeting LRRK2 activity could be protective and beneficial for brain disorders with an inflammatory component." (PMID 41008629, 2025). "Overall, our study corroborates the anti-inflammatory properties of LRRK2 kinase inhibition in preclinical models of AD- and PD-related neuroinflammation and supports the hypothesis that targeting LRRK2 activity could be protective and beneficial for brain disorders with an inflammatory component." (PMID 37443833, 2023). "Thus, our findings confirmed that LRRK2 kinase inhibition has anti-inflammatory effects and could be protective and beneficial for brain disorders with an inflammatory component." (PMID 37443833, 2023). "In addition to the PD-related state, lowering LRRK2 kinase activity has been shown to have anti-inflammatory properties even in a mouse model with spinal cord injury, thus supporting the idea that LRRK2 could be targeted and be beneficial for different brain diseases with an inflammatory component." (PMID 37443833, 2023). "This included brain disease traits with expression in the nervous system (antisense to APP and two antisense lncRNAs to MAPT) as well as immune-related diseases and enrichment in immune cells (antisense to LRRK2 and C9orf72)." (PMID 30610612, 2019).
mitochondrial disease (3 papers, 2019 to 2025). "However, there are important differences between mitochondrial diseases and LRRK2-associated mtDNA dysfunction." (PMID 40440058, 2025). "In addition, LRRK2 kinase activity inhibitors could also provide a way to increase mitophagy in general, which could be beneficial in idiopathic PD, or indeed, in other non-related conditions where increased clearance of mitochondria could be beneficial, such as mitochondrial diseases." (PMID 34340748, 2021).
neurodevelopmental disorder (3 papers, 2024 to 2025). A behavioral and cognitive disorder with onset during the developmental period that involves impaired or aberrant development of intellectual, motor, or social functions. "Thus far, investigations of LRRK2 association with neurodevelopmental disorders have been inconclusive." (PMID 40371391, 2025). "A key question for future investigation is the potential involvement of LRRK2 in protecting against neurodevelopmental disorders." (PMID 40371391, 2025). "With regards to human genetic analysis, it may be useful to investigate a potential association between LRRK2(GOF) variants and neurodevelopmental disorders." (PMID 40371391, 2025).
adenocarcinoma (1 paper, 2024). A common cancer characterized by the presence of malignant glandular cells. "In contrast, the large tumors formed in LRRK2 KI mice exhibited extensive and confluent high-grade dysplasia, loss of nuclei polarity and lamina propria invasion, characteristic of adenocarcinoma." (PMID 38607004, 2024).
central nervous system disease (1 paper, 2023). "We enrolled two wild‐type (WT) healthy volunteers who had not been diagnosed with a central nervous system disease, and 2 PD patients who had the LRRK2 G2019S mutation verified." (PMID 37672887, 2023).
intestinal disorder (1 paper, 2024). A non-neoplastic or neoplastic disorder that affects the small or large intestine. "It opens new perspectives on the possible role of LRRK2 in GI physiology and should prompt further studies of enteric glial LRRK2, which could become a new target for modulation of the intestinal tract functions and intestinal disorders." (PMID 38279293, 2024).
LRRK2 also shares sentences with these, for which no sentence is quoted: rheumatoid arthritis (5 papers); neurotoxicity (4); Ataxia (3); autosomal dominant Parkinson disease 8 (3); cholangiocarcinoma (3); late-onset Parkinson disease (3); metabolic disorders (3); parkinsonian disorder (3); psoriasis (3); astrocytoma (2); autism spectrum disorder (2); Autoimmunity (2); behavioral disorders (2); bladder cancer (2); brain cancer (2); cardiovascular disease (2); colon (2); hematological cancers (2); hyperlipidemia (2); Immunodeficiency (2); Insulin resistance (2); intrahepatic cholangiocarcinoma (2); mood disorder (2); Neurodegeneration (2); spinal muscular atrophy (2); type 1 diabetes (2); type 2 diabetes (2); acute liver failure (1); acute myeloid leukemia (1); advanced sleep phase syndrome (1).
A further 92 diseases each share a sentence with LRRK2 in 1 paper.